BRAF (B-Raf proto-oncogene, serine/threonine kinase)
Diseases named in the same sentence as BRAF in open-access papers (continued):
Sharing a sentence is not in itself a finding about the gene and the disease.
melanoma (continued). "Therefore, we sought to compare overall survival of patients with advanced BRAF mutant melanoma treated with either front‐line BRAF/MEKi, aPD‐1, or niv/ipi." (PMID 31677253, 2019). "Interestingly, Wee1 kinase was identified as a downstream target of BRAF V600E and its expression was found to be upregulated in melanoma as compared to benign nevi." (PMID 30728057, 2019). "Finally, the two additional follow‐up fluids were BRAF p.V600E‐positive ASC from a melanoma patient." (PMID 31529604, 2019). "Another study observed that in melanoma, miR‐514 contributed to the sensitivity of BRAF inhibitors." (PMID 30499222, 2019). "Finally, we combined the most promising Chk and Wee1 inhibitors AZD7762 and MK-1775, since they showed high degrees of synergism in parental but also in several BRAF inhibitor-resistant melanoma cell lines, over longer periods of time." (PMID 30728057, 2019). "Notably, MEK1 mutations are often associated with either BRAF or NRAS mutations; however, the combinatorial effect of that association on the pathogenesis and treatment of melanoma has been poorly investigated." (PMID 30934534, 2019). "NGS revealed 118 (26%) of 446 melanomas with no mutation, 42% with BRAF mutations, 25% with NRAS mutations, 4.9% with KIT mutations, and 2.0, 2.7 and 2.7% with HRAS, KRAS and PIK3CA mutations, respectively." (PMID 31277584, 2019). "Indeed, recent reports have focused on the immunomodulatory effects of BRAF/MEK inhibitors on the tumor microenvironment in melanoma-bearing hosts." (PMID 31514399, 2019). "Small-molecule inhibitors of BRAF such as vemurafenib and dabrafenib have shown remarkable results as molecularly targeted therapies for melanoma, especially when used in combination with MEK inhibitors, including the MEK inhibitor AZD6244 (also known as selumetinib or ARRY-142886)." (PMID 31399133, 2019). "The expression of tissue factor was investigated after the treatment with the BRAF inhibitor Dabrafenib and the MEK inhibitor Trametinib in the BRAFv600e mutated melanoma cell lines A-375 and SK-MEL-28, together with its ability to activate the coagulation cascade." (PMID 31467489, 2019). "The BRAF oncogene has been considered as one of themost important markers that play a role in the pathogenesis of tumors including thyroid, ovarian, and colorectal carcinoma, as well as malignant melanoma." (PMID 31531096, 2019). "However, DC-ATA was clinically tested in melanoma patients in an era before the widespread availability of anti-PD-1 monoclonal antibodies or BRAF/MEK inhibitors." (PMID 31614482, 2019). "Accordingly, JACKS’ estimated BRAF essentiality in the Avana data set is large in BRAF mutant melanoma lines, weak in BRAF-mutant colon cancer lines, and negligible in most other lines (median, −1.39 vs. −0.35 vs. 0.03), regardless of the data set used in estimation." (PMID 30674557, 2019). "In addition, the functional abrogation of tumor-associated myeloid cells, such as myeloid-derived suppressor cells (MDSCs) and tumor-associated macrophages (TAMs), have been shown to improve the anti-melanoma effects of BRAF/MEK inhibitor-resistant melanoma." (PMID 31514399, 2019). "Therefore, BRAF (V600E) serves as a molecular target and BRAF inhibitors have remarkable clinical value in treating melanomas." (PMID 30463359, 2018). "All three melanoma cell lines, A2058, A375, and SK-MEL-28, harbor BRAF mutation." (PMID 29929490, 2018). "Maldonado JL found BRAF mutations in 2/21 mucosal melanomas, Cohen Y in 1/25, whereas Edwards RH found none BRAF mutation in 13 mucosal melanomas." (PMID 29492238, 2018).
melanoma (continued). "The fact that melanoma cells express activating mutations in BRAF, but not in A-RAF or C-RAF, allowed the development of the small-molecule drug PLX4032, an orally available and well-tolerated selective BRAF inhibitor." (PMID 30191142, 2018). "Therefore, basal protein expression levels from early passage Stage III derived melanoma cells was sufficient to approximate the in vitro response to the ATP-competitive MEK inhibitor, selumetinib and this was unrelated to BRAF/NRAS mutational genotype." (PMID 30116025, 2018). "Currently, BRAF/MEK inhibitor combination therapy is FDA-approved for the treatment of melanoma." (PMID 30559933, 2018). "Consequently, melanomas resistant to BRAF/MEK inhibitors have increased mitochondria biogenesis and metabolically switch to oxidative phosphorylation (OXPHOS) through upregulation of MITF and PGC1α." (PMID 30651927, 2018). "Although the BRAF V600 mutation is an oncogenic driver mutation involved in cellular proliferation, it is considered insufficient to induce melanoma in the absence of other cytogenetic abnormalities." (PMID 29148538, 2018). "BRAF, NRAS and Kit mutations stand out in pathogenesis and targeted therapy of melanoma." (PMID 29492238, 2018). "The genomic landscape of melanoma, performed by The Cancer Genome Atlas (TCGA) on 333 melanoma samples delineated 4 genomic subtypes, i.e., triple wild-type (WT), BRAF mutant, NRAS, HRAS or KRAS mutant, and NF1 mutant, as well as three transcriptomic subclasses, i.e., immune, keratin and MIFT-low." (PMID 29743104, 2018). "Biomarkers are also needed to help decide the type of first-line treatment, e.g., whether BRAF-mutant melanoma should be treated by use of targeted or immunotherapy, therapy sequencing, and/or by a combination of treatments." (PMID 30002656, 2018). "We also show that 17-AAG can suppress both cell proliferation and the paradoxical activation of ERK in NRAS melanoma cells treated with BRAF inhibitor N-(3-(5-(4-chlorophenyl)-1H-pyrrolo[2;3-b] pyridine-3-carbonyl)-2,4-difluorophenyl) propane-1- sulfonamide (PLX4032 or vemurafenib)." (PMID 29481571, 2018). "Thus, we expected PI3K/AKT signalling would confer robust resistance to BRAF/MEK inhibition in both these melanoma cell models." (PMID 30237495, 2018). "Additionally, other factors, such as an enhanced reactive oxygen production appears to be critical in the success for the treatment of melanoma cells that acquired resistance to the BRAF chemotherapy." (PMID 30191142, 2018). "Chromatin remodeling along with the combination of proteasome inhibitors might play a role in resynthesizing cells to BRAF inhibitors, allowing a different therapeutic approach towards battling melanoma." (PMID 29795041, 2018). "BRAF promoted immunosuppressive IL-1 secretion in the stromal cells of melanoma patients." (PMID 30135516, 2018). "This study investigated the utility of protein expression phenotyping to provide an integrated assessment of gene expression programs in BRAF/NRAS melanoma which would be useful for prognosis and may predict response to MEK inhibition." (PMID 30116025, 2018). "Second, we investigated whether E2F1 depletion acts synergistically with BRAF inhibitors to enhance its pro-apoptotic effect on melanoma cells." (PMID 29743521, 2018). "In BRAF inhibitor-resistant melanoma cells, upregulation of AEBP1 mediated by hyperactivation of the PI3K/Akt-CREB (cAMP response element-binding protein) pathway activated NF-κB activity by accelerating IκBα degradation, thereby conferring acquired resistance to BRAF (V600E) inhibition." (PMID 30097586, 2018). "Another study in this field is the COWBOY study in BRAF-mutant melanoma patients." (PMID 30595751, 2018).
melanoma (continued). "Since AcAc, the second ketone body which rises in circulation upon a ketogenic diet, was described to increase proliferation in BRAF V600E melanoma cells, we performed cell proliferation assays in the presence of this metabolite over 5 days in parallel to the 3-OHB experiments." (PMID 29942509, 2018). "We evaluated longitudinal tracking of BRAF V600E in circulating cell-free DNA (cfDNA) as a marker of treatment response to BRAF inhibitor (BRAFi) combination therapies in non-melanoma solid tumors included in the Copenhagen Prospective Personalized Oncology (CoPPO) program." (PMID 30220966, 2018). "Furthermore, melanoma cells with acquired resistance to BRAF inhibition remained as sensitive to the combination as their BRAF sensitive counterparts." (PMID 29464063, 2018). "Three-year landmark data are also available from the phase 3 coBRIM study (NCT01689519), which evaluated cobimetinib plus vemurafenib vs placebo plus vemurafenib in patients with advanced BRAF V600-mutant melanoma; reported 3-year overall survival rates were 37.4 and 31.5%, respectively." (PMID 29148538, 2018). "Our data provide a clear rationale for the combination of targeted therapy and immunotherapy for melanoma and may further expand the understanding of BRAF and MEK inhibitor effects on the immune system." (PMID 29346301, 2018). "Even within this small cohort, the data suggest that pharmacological inhibition of ALK combined with BRAF inhibitors might represent an interesting therapeutic opportunity for a subset of melanoma patients." (PMID 30290811, 2018). "Concurrent mutations in BRAF and diminished PTEN expression are common in human melanomas." (PMID 30086162, 2018). "In conclusion, our data show that the combination of quisinostat and flavopiridol treatment inhibits melanoma cell viability synergistically by inducing apoptosis, independent of driver mutations and acquired BRAF inhibitor resistance." (PMID 29464063, 2018). "Importantly, USP28 expression was up-regulated after vemurafenib treatment in all of the BRAF (V600E) melanoma cell lines tested." (PMID 29880484, 2018). "Finally, depletion of SOX10 sensitizes mutant BRAF melanoma cells to RAF inhibitors in vitro and in vivo." (PMID 29295999, 2018). "BRaf inhibitors used against BRaf-mutated melanomas, such as vemurafenib or dabrafenib, are unlikely to prove any meaningful clinical effect as targeted agents in KRAS-mutated NSCLC, since KRAS and BRaf activating mutations are mutually exclusive." (PMID 29455666, 2018). "We then investigated whether SOX10 is a mediator of the ERK-dependent regulation of FOXD3 in mutant BRAF melanoma cells." (PMID 29295999, 2018). "According to the data presented here this could probably be achieved by blocking CEACAM1 in some melanoma subsets (e.g. BRAF wildtype with high CEACAM1 expression)." (PMID 30089785, 2018). "The consensus central nodes for melanoma cell lines with and without BRAF mutations were mapped to candidate drugs using DGIdb." (PMID 30042785, 2018). "In addition, in vitro and in silico studies have shown that BBR reduces levels of ERK and p38 MAPK; BBR also silences BRAF/ERK signaling in melanoma cells." (PMID 29565994, 2018). "BRAF and NRAS mutation status and BRAF inhibitor sensitivity of melanoma cell lines." (PMID 29450192, 2018). "Similarly, BRAF melanomas will overcome BRAF inhibition via the reactivation of the MEK–ERK cascade." (PMID 30518036, 2018). "Together, these data suggest that the combination treatment is more potent than single drugs in killing the MICs in most of melanoma tested, and the mutation status of BRAF or NRAS did not influence the effects." (PMID 30185782, 2018). "Despite the recent advancement in treating melanoma, options are still limited for patients without BRAF mutations or in relapse from current treatments." (PMID 30185782, 2018).
melanoma (continued). "To further confirm this finding, we introduced BRAF(ΔNVTAP/V471F)* into BRAF(V600E)-dependent melanoma cell lines by lentiviral transductions and found that its expression downregulated phospho-ERK1/2 and inhibited cell growth in vitro and xenograft tumor growth in vivo." (PMID 29930381, 2018). "In contrast, if ectopic expression of Grm1 is turned on first, then regardless of wild-type or mutated BRaf in the melanocytes melanoma development is the consequence." (PMID 29464040, 2018). "In the LMC, CD8+ T cell and NK cell scores were strongly predictive of melanoma-specific survival in double-WT tumors, but less so in BRAF-mutated and not at all in NRAS-mutated tumors; these differences were not matched by differences in cell scores." (PMID 29664013, 2018). "Importantly, ERK activation also appeared to play a role in maintaining RIP1 expression through upregulation of Snail1 and downregulation of CYLD in melanoma cells acquired resistance to BRAF/MEK inhibitors." (PMID 29880840, 2018). "Moreover, we demonstrate that suppression of CYLD by ERK1/2 signaling plays an important role in maintaining RIP1 expression, and that melanoma cells with acquired resistance to BRAF inhibitors are more critically dependent on RIP1 for survival." (PMID 29880840, 2018). "Further promise in this area is illustrated by the recent report that miRNA-211-5p was induced within exosomes in response to vemurafenib treatment of BRAF-mutant melanoma cells, and as such, may represent a potential biomarker or therapeutic target." (PMID 29343260, 2018). "Interestingly, down-regulation of several components of the SCF ligase complex have previously been demonstrated to limit sensitivity to BRAF inhibition in melanoma cell lines." (PMID 29880484, 2018). "It therefore seems that multiple mechanisms may cooperatively contribute to the increased activation of NF-κB in melanoma cells with acquired resistance to BRAF inhibitors." (PMID 29880840, 2018). "As dabrafenib and vemurafenib have different potencies against mutant BRAF in isolated kinase assays, we determined equipotent concentrations of drug required to inhibit pERK in 1205Lu BRAF‐mutant melanoma cells and identified 100 nm dabrafenib to have equivalent effects to 1 μm of vemurafenib." (PMID 29112787, 2018). "A second metabolic switch in BRAF inhibitor-resistant melanoma cells was found on the level of PDK." (PMID 30456204, 2018). "Our findings not only delineate a signaling network that governs the FOXD3-mediated adaptive resistance to RAF inhibitors in mutant BRAF melanoma but also demonstrate an intricate regulatory switch of SOX10 transcription activity that involves interplay between phosphorylation and sumoylation." (PMID 29295999, 2018). "Additionally, all IDTCs had increased activation of MAPK, AKT, and mTOR pathways, as previously demonstrated for the BRAF mt melanoma IDTCs." (PMID 29492189, 2018). "The research conducted on inhibitors of mutant BRAF in NSCLC is limited; however, extensive work has been done on elucidating mechanisms of resistance to BRAF inhibitors in melanoma and may provide parallels to mechanisms in lung cancer." (PMID 29973561, 2018). "The purpose of this study is to determine whether ABCB5 is highly expressed in BRAF inhibitor-resistant melanoma cells and to evaluate whether ABCB5 is involved in the development of resistance to BRAF inhibitors in cutaneous melanoma." (PMID 29929490, 2018). "The availability of specific inhibitors targeting mutated BRAF and the downstream MAPK signalling pathway or other kinases activated in melanoma, together with immunotherapies that de-block inhibition of T cell responses against the tumour, offer potent ways to fight this cancer." (PMID 30290811, 2018). "Having documented that SCD1 expression increases with melanoma progression, we hypothesized that SCD1 may be associated with resistance to targeted agents directed against BRAF and MEK." (PMID 30558661, 2018).
melanoma (continued). "In this report, we demonstrate that melanoma cells that either harbor activating NRAS mutations with BRAFWT or harbor the BRAFV600E mutation with wild-type NRAS, the BRAF is bound by HSP90 and under certain conditions is subject to degradation by HSP90 inhibition with 17-AAG." (PMID 29481571, 2018). "Resistance to BRAF inhibitors limits their clinical benefit in melanoma patients." (PMID 30429474, 2018). "RAF kinase inhibitors are clinically active in patients with BRAF (V600E) mutant melanoma." (PMID 29880484, 2018). "The intrinsic resistance is especially relevant for vemurafenib or dabrafenib therapy, with about 20% of patients with BRAF-mutated melanoma not-responsive." (PMID 29946532, 2018). "How is RIP1 upregulated in melanoma cells that have acquired resistance to BRAF inhibitors?" (PMID 29880840, 2018). "Hence, resistant BRAF mutant melanoma cells are more sensitive to the GLS inhibitor BPTES, which reduces ATP levels in resistant cells but not in parental cells." (PMID 30456204, 2018). "Although the role of FOXD3 as a mediator of adaptive resistance to RAF inhibitors in mutant BRAF melanoma cells has been well established, how ERK signaling controls FOXD3 expression remains unclear." (PMID 29295999, 2018). "There are several different mechanisms by which melanoma develops BRAF inhibitor resistance." (PMID 29929490, 2018). "Therefore, we focused on co-module #12, which was sensitive to BRAF inhibition and included strong melanoma characteristics, and was also one of the highly reproducible modules among the 10 trials." (PMID 29950679, 2018). "Sequencing of mutation hotspots in five melanoma driver genes (BRAF, NRAS, KRAS, GNAQ, GNA11) did not reveal any changes in 9/11 patients." (PMID 30558566, 2018). "Furthermore, it has been noted that in BRAF mutant melanoma, patient tumor responses are directly correlated with pERK down-regulation." (PMID 29880484, 2018). "A key example of how genomic alterations may impact tumor visibility is illustrated in the case of BRAF-mutant melanoma." (PMID 29780391, 2018). "We found that melanoma cells lacking NRAS or BRAF mutations (WT/WT) were resistant to 6-thio-dG and Gamitrinib as single agents or in combination, as these compounds did not induce cell death." (PMID 29695835, 2018). "Moreover, JMJD6 expression levels are higher in the samples with HRAS and BRAF mutations compared to samples with wild type HRAS and BRAF, suggesting that JMJD6 is upregulated by RAS signaling in these melanomas." (PMID 30619488, 2018). "However, little has been studied regarding the roles of ABCB5 on BRAF inhibitor-resistant melanoma cells." (PMID 29929490, 2018). "While many studies support the causal role of activating BRAF and NRAS mutations in melanoma progression, opposing data suggest that the contribution of PI3K-Akt pathway to this disease may be variable." (PMID 30166456, 2018). "Our recent single cell study resolved the heterogeneity of cellular states in cultures of melanoma cells which harbor either BRAF or NRAS mutations, or none of them." (PMID 29614062, 2018). "Due to the known MoA (e.g., binding to BRAF mutants and inhibiting the downstream signaling pathway) and the target population (e.g., melanoma with BRAF p.V600E), it is much easier to develop predictive biomarker (e.g., BRAF p.V600E) for personalize treatment using modern drug." (PMID 29765977, 2018). "Importantly, the presence or absence of the M-MITF-PGC1α regulatory axis has stratification potential in melanoma and informs on the efficacy of BRAF inhibitor treatments." (PMID 30310055, 2018). "The AKTQ79K mutation, for instance, was identified in a single BRAF inhibitor-resistant melanoma and was shown to selectively promote BRAF inhibitor resistance in PTEN-wild type melanoma cells that display weak AKT phosphorylation in response to BRAF inhibition." (PMID 30237495, 2018).